GEMIN7 (gem nuclear organelle associated protein 7)
Description:
The SMN complex catalyzes the assembly of small nuclear ribonucleoproteins (snRNPs), the building blocks of the spliceosome, and thereby plays an important role in the splicing of cellular pre-mRNAs. Most spliceosomal snRNPs contain a common set of Sm proteins SNRPB, SNRPD1, SNRPD2, SNRPD3, SNRPE, SNRPF and SNRPG that assemble in a heptameric protein ring on the Sm site of the small nuclear RNA to form the core snRNP (Sm core). In the cytosol, the Sm proteins SNRPD1, SNRPD2, SNRPE, SNRPF and SNRPG are trapped in an inactive 6S pICln-Sm complex by the chaperone CLNS1A that controls the assembly of the core snRNP. To assemble core snRNPs, the SMN complex accepts the trapped 5Sm proteins from CLNS1A forming an intermediate. Binding of snRNA inside 5Sm triggers eviction of the SMN complex, thereby allowing binding of SNRPD3 and SNRPB to complete assembly of the core snRNP.
Synonyms: FLJ13956; SIP3
Tractability: No criterion of Open Targets' tractability assessment is met for any kind of drug.
Gene: Protein-coding gene on chromosome 19 (45,075,575 to 45,091,518, forward strand). Ensembl gene ENSG00000142252.
Subcellular location: Nucleus, nucleoplasm; Nucleus, gem; Cytoplasm
Subcellular location (Human Protein Atlas): Cytosol; Nucleoplasm
Pathways (Reactome):
Disease: SARS-CoV-2 modulates host translation machinery
Metabolism of RNA: snRNP Assembly
Gene Ontology:
Molecular function: protein binding; RNA binding
Biological process: spliceosomal snRNP assembly; mRNA splicing, via spliceosome
Cellular component: cytoplasm; cytosol; Gemini of Cajal bodies; nuclear body; nucleoplasm; SMN complex; SMN-Sm protein complex; Sm-like protein family complex
Genetic constraint (gnomAD): Loss-of-function variants: 7 observed, 9.2 expected, observed/expected ratio (o/e) 0.76, 90% interval 0.43 to 1.42. That is too few expected variants to judge how well the gene tolerates losing a copy. Missense variants: 159 observed, 185.36 expected, observed/expected ratio (o/e) 0.86, 90% interval 0.75 to 0.98. Synonymous variants: 68 observed, 74.87 expected, observed/expected ratio (o/e) 0.91, 90% interval 0.75 to 1.11.
Homologues: Orthologues: chimpanzee GEMIN7 (99% identical), macaque GEMIN7 (98% identical), macaque GEMIN7 (97% identical), dog GEMIN7 (86% identical), guinea pig GEMIN7 (85% identical), pig GEMIN7 (84% identical), rat Gemin7 (82% identical), mouse Gemin7 (81% identical), rat Gemin7l1 (81% identical), zebrafish gemin7 (47% identical), tropical clawed frog gemin7 (44% identical), Caenorhabditis elegans C24H11.5 (21% identical).
Diseases named in the same sentence as GEMIN7 in open-access papers:
GEMIN7 is named in the same sentence as 11 diseases in open-access papers, as found by Europe PMC text mining. Sharing a sentence is not in itself a finding about the gene and the disease. The quoted sentences say what the papers report.
Alzheimer disease (1 paper, 2023). A progressive, neurodegenerative disease characterized by loss of function and death of nerve cells in several areas of the brain leading to loss of cognitive function such as memory and language. "Among the top 20 associated genes, the gene-set enrichment analysis showed that the GWAS catalog gene-set of Alzheimer’s disease or pleiotropy had 4 genes (GEMIN7, MARK4, PPP1R37, and NKPD1) overlapped (p = 1.74 × 10−7, adjusted-p = 3.16 × 10−4)." (PMID 37391420, 2023).
cancer (2 papers, 2021 to 2022). A tumor composed of atypical neoplastic, often pleomorphic cells that invade other tissues. "A previous study reported that GEMIN7, a component of the survival motor neuron complex, is involved in the biogenesis of the small nuclear ribonucleoprotein complex; however, its role in cancers is rarely reported." (PMID 33685397, 2021). "Significantly altered functions, pathways, and gene networks revealed alterations in several key genes and cancer-related pathways that may have importance for NSCLC transformation, including FAM83A, ZNF696, UBE2C, RECK, TIMM50, GEMIN7, and XPO5." (PMID 35309509, 2022). "Moreover, gene interaction networks revealed several key genes and cancer-related pathways that may role for early NSCLC transformation and disease progression, including FAM83A, ZNF696, UBE2C, RECK, TIMM50, GEMIN7, and XPO5." (PMID 35309509, 2022).
GEMIN7 also shares sentences with these, for which no sentence is quoted: bacterial infection (1 paper); breast carcinoma (1); cognitive decline (1); depression (1); infection (1); leukemia (1); lung carcinoma (1); non-small cell lung carcinoma (1); retinal degeneration (1).